HIF1A (hypoxia inducible factor 1 subunit alpha)
Diseases named in the same sentence as HIF1A in open-access papers (continued):
Sharing a sentence is not in itself a finding about the gene and the disease.
prostate carcinoma (continued). "In conclusion, our findings indicate that ERβ2 binds to and stabilizes HIF-1α and furthermore, is co-recruited to key HIF-1α elements in HIF-1α regulated genes thereby enhancing the activity of HIF-1α during normoxic conditions in prostate cancer cells." (PMID 26010887, 2015). "Understanding the miRNA regulatory network in HIF1α-controlled hypoxia response will provide not only new insight into hypoxia adaption and angiogenesis but also therapeutic targets for prostate cancer." (PMID 26205124, 2015). "To be noted, we did not observe any alteration of HIF1α mRNA levels in DU145 and PC-3 prostate cancer cells overexpressing miR-182, which is consistent with the working model of the regulation of HIF1α by PHD2 and FIH1." (PMID 26205124, 2015). "Sphingomab inhibited accumulation of HIF-1α in a concentration-dependent manner in human PC-3 prostate cancer cells." (PMID 25915662, 2015). "Together, we provided evidence for a novel mechanism regulating HIF-1α during hypoxia adaption and angiogenesis in prostate cancer." (PMID 26205124, 2015). "HIF-1α has been found to mediate EGF-induced prostate cancer cell EMT phenotype and STAT3 downstream of ROS is implicated in EGF-induced HIF-1α transcription and protein expression." (PMID 26273424, 2015). "We also checked the expression of VEGF, a known HIF1α target gene, in these two prostate cancer cell lines." (PMID 26205124, 2015). "As expected, miR-182 overexpression resulted in an elevation of HIF1α protein levels in either DU145 or PC-3 prostate cancer cells." (PMID 26205124, 2015). "DEC1 association with the PKM2/HIF-1α complex was also confirmed in DU145 cells, another metastatic prostate carcinoma cell line." (PMID 26183399, 2015). "Here, we show that ERβ2 also increased activity of a luciferase reporter driven by the HIF-1α-dependent Twist1 promoter in LNCaP prostate cancer cells and that this effect was dependent upon the HIF-1α response element." (PMID 26010887, 2015). "Melatonin suppresses tumor angiogenesis by inhibiting HIF-1α expression and stabilization in prostate cancer and HCT116 colon cancer cells under hypoxic condition in vitro." (PMID 24416386, 2014). "But PC-3M being a highly invasive prostate cancer model provides the opportunity to investigate the role of MSeA on HIF-1α regulation and its downstream targets." (PMID 24515947, 2014). "Consistent with our results, it has been found that the 17-AAG not only destabilizes the HIF-1α protein in prostate cancer cells but also disrupts STAT3- HIF-1α activation axis in pancreatic and gastric cancer cells." (PMID 24658058, 2014). "According to previous reports, HIF-1α can be induced by many molecules such as guanylate cyclase as well as protein kinase C in aged skin, p70S6K1 in prostate cancer cells and PI3K/Akt in myotubes." (PMID 25271630, 2014). "We previously found that HIF-1α can be strongly induced by acute arsenic treatment in prostate cancer cells under normoxia condition." (PMID 24413338, 2014). "Expression of hypoxia-inducible factor (HIF)1α increases the risk of castrate-resistant prostate cancer (CRPC) and metastases in patients on androgen deprivation therapy (ADT) for prostate cancer (PC)." (PMID 24464861, 2014). "Berberine increased radiosensitivity of prostate cancer cells and xenografts in a dose dependent manner, and this was correlated with the inhibition of HIF-1α and VEGF expression." (PMID 24886405, 2014). "Briefly, endogenous p300 was immunoprecipitated from PC3 human prostate cancer cells under hypoxic conditions in the absence and presence of ETPs, and co-immunoprecipitated HIF-1α was detected by Western blotting." (PMID 24775564, 2014). "In the current investigation we show for the first time that MSeA elevates REDD1 expression in invasive prostate cancer cells under hypoxic conditions and maintains lower levels of HIF-1α." (PMID 24515947, 2014).
prostate carcinoma (continued). "Our findings suggest that nobiletin regulates VEGF expression through down-regulating AKT and HIF-1α in prostate cancer cells." (PMID 25342300, 2014). "A study in a human prostate cancer model has shown that hypoxic activation of HIF1A signalling results in a similar effect on these metabolites." (PMID 24837709, 2014). "In our previous report, we had documented MSeA-induced downregulation of HIF-1α in invasive prostate cancer cells." (PMID 24515947, 2014). "Altogether, these results demonstrate a role for ARRB1 as a regulator of hypoxia-mediated HIF1A transcriptional activity in prostate cancer cells." (PMID 24837709, 2014). "The finding that the predicted upstream regulatory genes included HIF1A, WT1, and EZH2 genes, reported to be associated with prostate cancer metastasis, suggests that the approach used had merit." (PMID 24448395, 2014). "HIF1α has been shown to bind Axl by ChIP analysis, and Axl signaling is stabilized in prostate cancer cells after treatment with CoCl2, a stabilizer of HIF1α." (PMID 25344858, 2014). "In other studies, HIF-1α facilitates apoptosis through a PKC-dependent mechanism in poly (I:C)-treated prostate cancer cells." (PMID 25101092, 2014). "Our previous studies showed that MSeA promotes apoptosis in invasive prostate cancer cells in part by downregulating hypoxia-inducible factor HIF-1α." (PMID 24515947, 2014). "In vitro co-immunoprecipitation studies in prostate cancer cell extracts demonstrated that these compounds disrupted the HIF-1α/p300 complex." (PMID 24775564, 2014). "In prostate carcinomas, not only the HIF-1α/AP-1 complex but also intracellular Zn2+ are involved in the induction of CD164 gene expression." (PMID 24094005, 2013). "Regulation of TGFβ1 expression by tissue oxygenation remains unstudied in CRC, although HIF-1α has been shown to increase TGFβ expression in prostate cancer cells." (PMID 24180698, 2013). "In our study, Phyllanthus extracts were noted to inhibit the glycolytic pathway and energy production in prostate cancer cells by down-regulating HIF-1α protein." (PMID 23690850, 2013). "In summary, this study demonstrates that miR-199b is dramatically down-regulated in prostate cancer and HIF-1α is a direct, functional target of it." (PMID 23594994, 2013). "Results from the analysis indicated that expression levels of STAT3-regulated pro-angiogenic genes, such as S1PR1, MMP9 and HIF1a, correlated with the density of tumor-infiltrating B cells in human prostate cancers." (PMID 23734190, 2013). "Our in vitro data is in accordance with a recent study demonstrating that treatment of human P493 B cells and PC3 prostate carcinoma cells with 10 mM NAC prevents Hif-1α stabilization and reduces VEGF secretion under hypoxic conditions (1% O2)." (PMID 23840457, 2013). "On the other hand, depletion of PRKAR2B, ADCK2, TRPM7, and TRIB2 significantly decreases the effect of TNFα on HIF-1α stability in osteosarcoma and prostate cancer cell lines." (PMID 22355351, 2012). "It has been also noted that forced over-expression of miR-21 in human prostate cancer DU145 cells led to increased expression of HIF-1α and VEGF mediated through Akt and ERK pathways, consistent with an increase in tumor angiogenesis." (PMID 23272057, 2012). "To examine if selected candidate hits can influence TNFα-mediated accumulation of HIF-1α in other cell types we determined HIF-1α nuclear buildup in prostate cancer cell lines." (PMID 22355351, 2012). "Pancreatic and prostate cancers have also been shown to involve Src-dependent induction of VEGF through the actions of HIF-1α." (PMID 22988500, 2012). "Chrysin significantly inhibited prostate cancer growth and angiogenesis with a decreased HIF-1α expression." (PMID 22844340, 2012). "Our study suggests that high nuclear expression of HIF1α and low EGFR expression in diagnostic biopsies of prostate cancer patients treated with RT ± ADT is associated with a good prognosis." (PMID 22546016, 2012).
prostate carcinoma (continued). "We have recently demonstrated that CAFs secrete MMPs which in turn stimulate ROS production in prostate carcinoma cells via a Rac1b/Cox2/HIF-1α pathway, finally leading to tumour growth and metastatic spreading." (PMID 22272371, 2012). "In the current study, CT exerted cytotoxicity against prostate cancer cells such as LNCaP, PC-3, and DU-145 cells under hypoxia and HIF-1α was dramatically induced under hypoxia, which was peaked at 6 h in PC-3 cells." (PMID 23243443, 2012). "Collectively, these observations demonstrate that the metastasis-suppressive activity of KAI1 is highly relevant to the down-regulation of CDCP1 and suppression of HIF-1α expression in prostate cancer." (PMID 22390300, 2012). "Consistent with our data, published results show the degradation of constitutively expressed HIF-1α in prostate cancer and hypoxia induced HIF-1α in B-cell lymphoma by selenium." (PMID 22804960, 2012). "CT exerted cytotoxicity against prostate cancer cells and suppressed HIF-1α accumulation and AEG-1 expression in hypoxic PC-3 cells." (PMID 23243443, 2012). "The ability of P3155 to inhibit HIF-1α activity was tested by evaluating levels of transcriptionally active HIF-1α protein expressed in the nuclei of prostate cancer cells PC-3 and DU145 exposed to hypoxia." (PMID 21819554, 2011). "Hypoxic stress increases the stability of the transcription factor HIF1α, allowing it to activate gene expression; however, even prostate cancer cell lines grown under normoxic conditions have been demonstrated to have high levels of HIF1α protein." (PMID 22135748, 2011). "In this study, we demonstrated that overexpression of miR-21 in human prostate cancer cells increased the expression of HIF-1α and VEGF, and induced tumor angiogenesis." (PMID 21544242, 2011). "This pathway also plays a key role in the control of HIF-1α translation and synthesis in prostate cancer cells." (PMID 21819554, 2011). "As HIF-1α protein is overexpressed in PC-3 prostate cancer cell line, it was mainly used for all further studies." (PMID 21819554, 2011). "The accumulation of HIF1α protein has been reported to be an early event in prostate cancer and high-grade prostatic intraepithelial neoplasia (HGPIN)." (PMID 20663134, 2010). "HIF1α, a major transcription factor essential in tumorigenesis, has been shown to be over-expressed in many types of tumors, including prostate cancer." (PMID 20663134, 2010). "We also conclude that in most cases of benign prostate hyperplasia and prostate cancers, the HIF1α isoform containing exon 12 is expressed at very low levels since LNCaP cells had high signals with the same primers (lane 5)." (PMID 20663134, 2010). "Immunostaining was performed on serial sections of benign prostate hyperplasia and HIF1α prostate cancer tissues." (PMID 20663134, 2010). "In human prostate cancer cells, basal-, growth factor-, and mitogen-induced expression of HIF-1α, was blocked by LY294002 and rapamycin." (PMID 19384426, 2007). "In conclusion, these results demonstrated that DCPA inhibits cell migration, proliferation, and HIF-1α expression in prostate cancer cells." (PMID 16884534, 2006). "Similarly, hypoxia‐inducible factor‐1 alpha (HIF‐1α) lactylation stabilizes this transcription factor in prostate cancer, amplifying angiogenesis and metabolic adaptation." (PMID 41454479, 2026). "However, another study revealed that ERRα physically interacts with and activates HIF-1α in a genetically controlled cell model of prostate cancer." (PMID 40723264, 2025). "Chrysin also decreases VEGF and HIF‐1α expression in metastatic prostate cancer cells in hypoxia; however, its clinical application may be limited by poor systemic bioavailability." (PMID 40781971, 2025). "In addition, lactylation can affect protein stability; for example, in prostate cancer, the lactylation of hypoxia inducible factor-1α (HIF-1α) improves its stability in normoxia, which in turn promotes angiogenesis in prostate cancer." (PMID 40724863, 2025).
prostate carcinoma (continued). "The MAO-A-dependent accumulation of reactive oxygen species (ROS) in prostate cancer cells stabilizes hypoxia-inducible factor 1-alpha (HIF1α), which in turn activates vascular endothelial growth factor (VEGF) and its neuropilin-1 receptor (NRP1) leading to stimulation of the Akt/FOXO1 pathway." (PMID 39714760, 2025). "Despite longstanding recognition of HIF1α as a master regulator of hypoxic adaptation, the precise mechanisms through which HIF1α influences lineage-specific transcriptional networks and therapeutic resistance in prostate cancer remain incompletely defined." (PMID 40643528, 2025). "Notably, in prostate cancer cell lines, the accumulation of HIF-1α induced by lactate likely involves lactylation." (PMID 40760493, 2025). "Genistein, has been recognized as a regulator of HIF-1α in prostate cancer cells (PC-3)." (PMID 40004215, 2025). "However, there is evidence that β-TrCP is overexpressed under hypoxia in prostate cancer cells and affects the stabilization of HIF-1α." (PMID 39940739, 2025). "Following this, the expression levels of apoptosis-related genes (BAX, Bcl-2), an angiogenesis gene (VEGF-C), a gene associated with progression and development (HIF-1α), genes involved in the EMT pathway (SNAIL and E-Cadherin), and a prostate cancer marker (KLK3) were evaluated using Real-Time PCR." (PMID 40388455, 2025). "Similarly, NSAID-treatment of prostate cancer cells resulted in reduced levels of HIF-1α and HIF-2α and down-regulated VEGF and Glut-1." (PMID 40408503, 2025). "This plasticity enables HIF1α to orchestrate distinct transcriptional programs tailored to microenvironmental oxygen availability, potentially contributing to prostate cancer progression through enhanced survival, invasiveness, and adaptation to hypoxic stress." (PMID 40643528, 2025). "Furthermore, the ERα-HIF-1α interaction in prostate cancer cells prevents the ubiquitination and subsequent degradation of HIF-1α, highlighting HIF-1α’s significance in scleral remodeling during myopia development." (PMID 39625993, 2024). "Previously, FCF was found to inhibit HIF-1α in a PC-3 prostate cancer cell line." (PMID 38473335, 2024). "In addition, HIF-1α has been found to exert a tumor-promoting role in prostate cancer via affecting autophagy." (PMID 38240686, 2024). "Furthermore, evodiamine significantly suppressed lactate-induced angiogenesis in prostate cancer cells by limiting histone lactylation and HIF-1α expression, which improved Sema3A transcription while downregulating PD-L1 transcription." (PMID 39690423, 2024). "Interestingly, in prostate cancer and pancreatic cancer, HIF1α exerts its physiological role on EMT indirectly through FoxM1 signaling and the PAFAH1B2 gene, respectively." (PMID 38361941, 2024). "Also, it was noted that digoxin inhibited the growth of prostate cancer cells in a murine model by downregulating HIF-1α-dependent gene expression and suppressing its protein synthesis." (PMID 39498340, 2024). "Moreover, a prostate cancer cell with elevated lactylation of HIF-1α activates KIAA1199, simulates KIAA1199-mediated angiogenesis and vasculogenic mimicry, and increases depolymerized hyaluronic acid." (PMID 38200523, 2024). "HIF1A is overexpressed in various tumors, including colon, breast, lung, and prostate cancer." (PMID 38928200, 2024). "Additionally, the decreased expression of FOXA1 in prostate cancer led to an increase in immunosuppressive macrophage infiltration, which is dependent on HIF-1α expression." (PMID 38287425, 2024). "Moreover, we found that GLDC correlated well with HIF-1α in gene expression 425 in TCGA prostate cancer patients." (PMID 37781511, 2023). "Furthermore, some studies have found that overexpression of miR-21 in prostate cancer tissue increases the expression of HIF-1α and VEGF by regulating VHL, thereby inducing angiogenesis." (PMID 37316504, 2023).
prostate carcinoma (continued). "Prostate cancer cell growth could be induced because hypoxia-inducible factor 1 alpha (HIF-1α) activation and stabilization by SENP1 result in promoted cyclin D1 and vascular endothelial growth factor (VEGF) levels, angiogenesis, and cell growth." (PMID 37502217, 2023). "Studies also reported that in prostate cancer, it was found that lactate can stabilize HIF1α through HIF1α lactylation under normal oxygen conditions and then regulate downstream pathways which further proved the diversified mechanism of lactate and lactylation in tumorigenesis." (PMID 37060186, 2023). "Chrysin, also known as 5,7-dihydroxyflavone, is another natural compound with anti-tumor properties, chrysin inhibits the growth and VM formation of prostate cancer cell line PC-3 by inhibiting HIF-1α, SPHK-1, and phosphorylation of the AKT/GSK-3β signaling pathway." (PMID 37810976, 2023). "Finally, their results showed VEGF expression in prostate cancer cells was reduced secondary to pharmacologic levels of melatonin, which they suggested to be a direct consequence of HIF-1α inhibition." (PMID 37191417, 2023). "Moreover, HIF-1α is highly expressed in a variety of malignant tumors, as well as in prostate cancer 9,10." (PMID 37781511, 2023). "Overall, our findings suggest that chrysin exerts anti-tumor activity by inhibiting SPHK-1/HIF-1α signaling and thus represents a potent chemotherapeutic agent for hypoxia, which promotes cancer progression and is related to poor prognoses in prostate cancer patients." (PMID 36139362, 2022). "Strikingly, a prior study also documented that Berberine could suppress HIF1α and inhibits the radio-resistance of prostate cancer." (PMID 35764613, 2022). "Moreover, EGF can induce Twist1 expression and prostate cancer cell invasion through a ROS/STAT3/HIF-1α signaling cascade." (PMID 36669020, 2022). "HIF1A exerts a tumor-promoting role in prostate cancer via affecting autophagy." (PMID 35317831, 2022). "HIF-1α functions as upstream mediator to stimulate Notch1 signaling in prostate cancer." (PMID 35773731, 2022). "SENP1 is linked to prostate cancer progression because SENP1 regulation of matrix metallopeptidase 2 (MMP2) and matrix metallopeptidase 9 (MMP9) through the hypoxia-inducible factor 1-alpha (HIF-1α) signaling pathway promotes progression." (PMID 35408841, 2022). "Recently, we and others have shown that Met blocks HIF-1α expression in some human cell lines derived from aggressive forms of hepatocellular and prostate carcinomas, suggesting a direct involvement of this chromatin-associated protein in the anticancer activity of Met." (PMID 36506071, 2022). "Moreover, Estrogen-Related Receptor Alpha (ERRα) can interact with HIF-1α, thereby inhibiting its ubiquitination and degradation to promote the adaptation of prostate cancer cells to hypoxic conditions." (PMID 35158804, 2022). "Thus, we provide scientific evidence that apigetrin exerts anti-cancer potential via inhibiting AKT, a key transmitter of HIF-1α and AR signaling in prostate cancer cells." (PMID 35740392, 2022). "Notably, silencing GHET1 promotes KLF2 expression, leading to HIF-1α/Notch1 inhibition and subsequent decrease in prostate cancer progression." (PMID 35773731, 2022). "Docetaxel regulated tumor glycolysis in prostate cancer cells in HIF-1a dependent manner." (PMID 36536346, 2022). "HIF-1α is highly expressed in various solid cancers including prostate cancer." (PMID 36139362, 2022). "Our previous study also confirmed that DAB2IP could promote EMT and metastasis in prostate cancer by inhibiting proteasome degradation of HIF1α through targeting PROX1 transcription." (PMID 35342346, 2022). "Thus, our data suggest that apigetrin exerts anti-cancer effects by inhibiting AKT, a central key of HIF-1α and AR signaling, in early-and late-stage prostate cancer cells." (PMID 35740392, 2022).